CDK5RAP2 (CDK5 regulatory subunit associated protein 2)
Diseases named in the same sentence as CDK5RAP2 in open-access papers (continued):
Sharing a sentence is not in itself a finding about the gene and the disease.
tumor (6 papers, 2013 to 2024). "The top associated region is located on canine chromosome 11 and reveals a complex genetic architecture with an abundance of risk haplotypes indicating involvement of the centrosomal cell cycle regulator CDK5 regulatory subunit-associated protein 2 (CDK5RAP2) in tumour development." (PMID 27158822, 2016). "The results showed that CDK5RAP2 expression was significantly higher in tumor tissues than in normal tissues." (PMID 36774351, 2023). "Although the average weight of the mice was similar in the two groups, the average weight of the tumor generated by CDK5RAP2-knockdown cells was considerably decreased compared to that in the control group." (PMID 36774351, 2023). "We performed IHC staining, and the results confirmed that CDK5RAP2 expression was increased in the tumor tissues compared to the normal tissues." (PMID 36774351, 2023). "Moreover, the four groups of SW480-luc cells were then injected into the tail vein of nude mice to detect the effect of CDK5RAP2 L or CDK5RAP2 S on tumor metastasis using live animal bioluminescence imaging (BLI)." (PMID 39048555, 2024). "IHC staining of tumor sections revealed that the levels of ALDH1, CD44, CD133, SOX2, Notch1, EZH2 and CCND1 were downregulated in CDK5RAP2-knockdown tumors." (PMID 36774351, 2023). "The analysis of these characteristics revealed that CDK5RAP2 expression was increased in human OSCC and closely related to tumor stage and metastasis." (PMID 36774351, 2023). "Furthermore, to investigate the correlation between CDK5RAP2 expression and the clinicopathological features of OSCC patients, we examined various clinical characteristics, such as gender, age, tumor size, differentiation grade, clinical stage, and lymph node metastasis." (PMID 36774351, 2023).
infection (3 papers, 2021 to 2024). The state of being infected such as from the introduction of a foreign agent such as serum, vaccine, antigenic substance or organism. "In the stable cells selected after infection, CDK5RAP2 knockdown efficiency was ~80%." (PMID 36774351, 2023).
neurological disorders (3 papers, 2017 to 2023). "Three genes are involved in developmental and neurological disorders: C3orf36, CDK5RAP2, CRY2." (PMID 29259192, 2017).
CDK5RAP2 also shares sentences with these, for which no sentence is quoted: dwarfism (2 papers); Ataxia (1); autism spectrum disorder (1); Cornelia de Lange syndrome (1); deafness (1); embryonic carcinoma (1); endolymphatic hydrops (1); Epileptic encephalopathy (1); glioma (1); infantile spasms (1); Macrocephaly (1); Mitosis (1); neurodevelopmental disorder (1); Pachygyria (1); primordial dwarfism (1); progeria (1); sensorineural hearing loss (1); status epilepticus (1); ZIKV congenital infection (1).